IGF2BP3 (insulin like growth factor 2 mRNA binding protein 3)
Diseases named in the same sentence as IGF2BP3 in open-access papers (continued):
Sharing a sentence is not in itself a finding about the gene and the disease.
tumor (continued). "and found that IGF2BP3 mRNA expression in tumor tissue was increased compared with that in normal endometrial tissue in The Cancer Genome Atlas (TCGA) dataset." (PMID 35676262, 2022). "Next, we analyzed the protein levels of IGF2BP2 and IGF2BP3 in different tumor types and normal tissues using the CPTAC dataset." (PMID 36686749, 2022). "We focused on the association between IGF2BPs and tumor prognosis, stemness, and the TME, as well as aid in exploring the role the IGF2BP3 in maintenance and self-renewal capacity of GSCs." (PMID 36686749, 2022). "Taken together, these results suggested the prognosis‐related tumor antigens including IGF2BP3, DPCR1, HOXD10, TRIM7, and ZIC5 were promising targets of being developed as mRNA vaccines against COAD." (PMID 35593226, 2022). "The abnormal upregulation of IGF2BP3 in tumorigenesis makes it a promising biomarker of tumor diagnosis." (PMID 36401176, 2022). "The positively correlated expression between IGF2BP3 and PD-L1 was found in 14/20 (70%) tumor specimens." (PMID 35148766, 2022). "A total of five tumor antigens with prognostic values were identified, including IGF2BP3, DPCR1, HOXD10, TRIM7, and ZIC5." (PMID 35593226, 2022). "We further validated the expression of IGF2BP2 and IGF2BP3 in tumor tissues (COAD, ESCA, and STAD) using qRT-PCR and immunofluorescence staining." (PMID 36686749, 2022). "Because of the important role of IGF2BP3 in risk score patterns, we used TCGA, GTEx CCLE, and Oncomine datasets to further understand IGF2BP3 in normal and tumor tissues." (PMID 35148766, 2022). "And the significant differences of the tumor microenvironment in different IGF2BP3 expression groups were explored." (PMID 35677634, 2022). "Using cell function assays, we uncovered that let-7g-5p inhibits the oncogenic role of IGF2BP3 in tumor progression, and regulates the activity of the KLK5/PAR2/AKT axis in GBC." (PMID 36313631, 2022). "A total of five selected tumor antigens, including IGF2BP3, DPCR1, HOXD10, TRIM7, and ZIC5 were identified as promising candidates for mRNA vaccine." (PMID 35593226, 2022). "Analysis on the expression of PKMYT1 and IGF2BP3 in the tumor distant metastasis group and lymph node metastasis group was performed using a tissue microarray and TCGA database, respectively." (PMID 35114989, 2022). "The IGF2BP3-mediated pathway leads to impaired NK cell recognition of transformed cells to facilitate tumor immune escape." (PMID 35148766, 2022). "In summary, our results reveal that upregulation of IGF2BP3, an important m6A regulator promoting tumor progression, is most likely the carcinogenic mechanism in the great majority of AML cases." (PMID 35217832, 2022). "IGF2BP3 protein was also significantly overexpressed in GBC tumor tissues based on IHC score quantification." (PMID 36313631, 2022). "Of particular interest, we observed that expression of insulin growth factor 2 mRNA binding protein 3 (IGF2BP3), a potential oncogene that can induce tumor development, was notably higher in AB+." (PMID 35615150, 2022). "Taken together, these data further shed light on the oncogenic role of IGF2BP3 in tumor progression." (PMID 35217832, 2022). "Overexpression of IGF2BP3 has been noticed in numerous tumor samples, and closely correlated to the progression and worse survival in COAD." (PMID 35593226, 2022). "Among these RBPs, IGF2BP3 mediated the greatest number of AASEs, and genes affected by these AASEs were enriched in tumor invasion and metastasis processes, such as “extracellular matrix organization”, “cell junction organization”, and “cell−matrix adhesion”." (PMID 35989380, 2022). "To clarify the mechanisms by which circNEIL3 mediates macrophage immunosuppressive properties, we performed RNA pull-down and RIP assays and found that circNEIL3 bound to IGF2BP3 at the same site in THP1-differentiated macrophages as in tumour cells." (PMID 35031058, 2022).
tumor (continued). "The expression of IGF2BP3 was positively correlated with macrophages, neutrophils, and dendritic cells and negatively correlated with tumor purity." (PMID 35148766, 2022). "All these data suggested that IGF2BP3 promotes the tumor development of NPC cells by regulating KPNA2 expressions." (PMID 35136045, 2022). "As illustrated in the subcutaneous tumor models, the tumor volumes and weights in IGF2BP3 silenced groups were lower than those in the control groups." (PMID 35136045, 2022). "The expression patterns of IGF2BP1 and IGF2BP3 can be described as “cancerous embryos”, as they are largely absent in adult tissues but are severely upregulated in various tumors and tumor-derived cells." (PMID 36237306, 2022). "It has been reported that IGF2BP3 can regulate gene expression and tumor progression by multiple mechanisms." (PMID 34657141, 2021). "IGF2BP3 functions as an oncofoetal factor in multiple tumour types, facilitating tumorigenesis by regulating the cell cycle, proliferation, and angiogenesis." (PMID 34802443, 2021). "Enhanced translation of IGF2 and IGF1R occurs via the de novo expression of the oncofetal RNA-binding proteins IGF2BPs (IGF2BP1, IGF2BP2, IGF2BP3) in different tumor types." (PMID 34440844, 2021). "Further, the m6A binding protein IGF2BP3 also takes part in the modulation of tumor immune evasion, showing a remarkably higher expression level in tumor cells than in normal tissue." (PMID 34586737, 2021). "The sporadic tumor showed two rare CNAs, being one at 6p15 and the other at 7p15.3, covering the IGF2BP3 gene, while the tumor from the syndromic patient only harbored common gains and losses." (PMID 35048058, 2021). "We analyzed the DEGs related to IGF2BP3 and tumor-related pathways regulated by differentially expressed m6A-modified genes." (PMID 34721530, 2021). "IGF2BP3 has been reported to be involved in the regulation of tumor cell fate (e.g. growth, survival, invasion, drug resistance) in multiple cancers." (PMID 34657141, 2021). "Then we analyzed the relationship between IGF2BP3 and other m6A regulatory factors and tumor immunity and metastasis." (PMID 34737950, 2021). "Differential expression analysis for these 24 m6A-related genes revealed that only IGF2BP1 and IGF2BP3 were highly expressed (|log2FoldChange| > 1, P<0.05) in SC tumor tissues relative to the normal group." (PMID 34621671, 2021). "In our research, the multivariate Cox regression analysis revealed that higher IGF2BP3 expression was associated with poor OS among all m6A-associated genes in GBM, and IGF2BP3 expression correlated with the tumor grade." (PMID 34721530, 2021). "Data from the CGGA database showed that IGF2BP3 expression increased when the tumor grade increased." (PMID 34721530, 2021). "Growing evidence has demonstrated that m6A modification is closely associated with tumorigenesis, tumor differentiation, tumor proliferation, tumor invasion and worse survival in BC patients, including METTL3, METTL14, WTAP, ALKBH5, IGF2BP2, IGF2BP3, and FTO." (PMID 33926554, 2021). "Among three, IGF2BP3 acts as a critical factor in the regulation of cancers, such as tumor cell proliferation, invasion, and chemoresistance." (PMID 34329193, 2021). "VEGF was an important growth factor for tumor angiogenesis; therefore, we further evaluated the effect of IGF2BP3 at HUVECs." (PMID 32993738, 2020). "IGF2BP3 has a critical role in modulating multiple mRNAs, thereby regulating tumor initiation and progression." (PMID 32719743, 2020). "IGF2BP3 silenced cells had a significantly decreased ability to form tumours in nude mice compared with vector‐transfected cells." (PMID 33094561, 2020). "qRT‐PCR and Western blotting confirmed that IGF2BP3 expression levels were lower in the tumours injected with IGF2BP3 depleted cells than that in the vector‐transfected cells." (PMID 33094561, 2020).
tumor (continued). "In agreement with that, tumors with higher IGF2BP3 expression were characterized by increased tumor size, advanced tumor stage, and lymph node metastasis." (PMID 33585234, 2020). "After analyzing the expression of these genes in different tumor types, we observed that IGF2BP3, NCAPG, and miR217 demonstrated higher expression in type 2 compared with type 1 KIRP (p < 0.05)." (PMID 33344459, 2020). "The loss of SIRT6 in PDAC tumor models was associated with upregulation of LIN28B and consequently increased expression of the let-7 targets HMGA2, IGF2BP1, and IGF2BP3." (PMID 32545414, 2020). "Down‐regulation of IGF2BP3 significantly decreased the xenograft tumour volume and tumour weight compared to the control group." (PMID 33094561, 2020). "Western blotting also showed that p‐STAT3 expression levels were lower in the tumours injected with IGF2BP3 depleted cells than that in the vector‐transfected cells." (PMID 33094561, 2020). "IGF2BP3 was expressed at higher levels in advanced stage tumours (T2‐T4) and at lower levels in early stage tumours (Ta‐T1)." (PMID 33094561, 2020). "As an RNA-binding protein (RBP), IGF2BP3 is of particular interest in tumorigenesis and tumor progression because of its over-expression in many tumors and regulation of cell growth and migration, as well as its response to drug." (PMID 33344459, 2020). "In summary, gC1qR suppressed the MM-inhibiting role of C1q and regulated CKS1B mRNA in promoting tumor proliferation via IGF2BP3 in 1q21-amplified MM." (PMID 32760394, 2020). "Concerning IGF2BP3 clinical relevance, it has been shown that this protein is a marker for aggressiveness, poor differentiation and tumor progression and it is related with an unfavorable prognostic and short survival times." (PMID 31440515, 2019). "Among the RBPs, insulin-like growth factor 2 mRNA-binding protein 3 (IGF2BP3) is of particular interest in tumorigenesis and tumor progression." (PMID 32010687, 2019). "Accordingly, different mediators of cell migration/invasion and cell adhesion have been reported as IGF2BP3 mRNA targets in different tumor types." (PMID 32010687, 2019). "Chromatin immunoprecipitation (ChIP) assays confirmed the direct binding of the transcription factors Nanog and NF-κB to the IGF2BP3 promoter, thus sustaining its expression in tumor cells and favoring the stemness and migration properties, respectively." (PMID 32010687, 2019). "Of those, the IGF2BP3-positive tumors generally display high metastatic behavior and poor outcome as well as increased tumor size, advanced tumor stage and lymph node metastasis." (PMID 32010687, 2019). "Altogether, these observations highlight a putative role of IGF2BP3 in promoting or preserving tumor cell subpopulations with stem cell features, thereby contributing to tumor establishment and progression." (PMID 32010687, 2019). "Limited but interesting evidence indicates that IGF2BP3 affects the interaction with the tumor microenvironment." (PMID 32010687, 2019). "Apart from copy number gain, IGF2BP3 has been confirmed to be negatively regulated by tumor-suppressive miRNA, namely miR-34a." (PMID 28399871, 2017). "Consistent with this concept, overexpression of IGF2BP3 enhanced tumor cell growth, migration and invasion, whereas knockdown of IGF2BP3 expression displayed opposite effects." (PMID 29212181, 2017). "Next, in vivo subcutaneous tumor formative assay was adopted to examine the tumorigenesis of H460 cells with IGF2BP3 expression in nude mice." (PMID 29212181, 2017). "The upregulation of IGF2BP3 was partly due to the silence of tumor-suppressive miR-34a in some GC samples." (PMID 28399871, 2017). "By known validated target mRNAs, IGF2BP3 can exert its activities in tumor initiation, proliferation and invasion." (PMID 29212181, 2017). "For example, it antagonizes let-7, a potent tumor suppressor, which post-transcriptionally represses the expression of metastasis-promoting genes including c-Myc and IGF2BP3." (PMID 29088808, 2017).
tumor (continued). "In vitro studies have revealed that IGF2BP3 up-regulated expression enhances tumor growth, drug-resistance and metastasis in various human cancers." (PMID 28458684, 2017). "For example, hypoxia-inducible microRNA-224 promotes the GC cell growth, migration and invasion by directly targeting RASSF8, but miR-34a can act as a tumor suppressor targeting IGF2BP3 in gastric carcinogenesis." (PMID 29296232, 2017). "Rescue experiments demonstrated that IGF2BP3 is a crucial target of miR-34a in GC because IGF2BP3 re-overexpression partly relieved the tumor-suppressive effect of miR-34a." (PMID 28399871, 2017). "The number of tumor nodules in lungs was significantly enhanced in IGF2BP3 overexpressing group compared with control group." (PMID 29212181, 2017). "Among the unique genes in this group is IGF2BP3, a member of mRNA protein binding family and an oncofetal protein that regulates expression of genes involved in tumor cell proliferation, chemo-resistance and metastasis." (PMID 28458684, 2017). "To identify circRNPs with a specific protein component, we focused on IMP3 (IGF2BP3, insulin-like growth factor 2 binding protein 3), a known tumor marker and RNA-binding protein." (PMID 27510448, 2016). "Analysis of IGF2BP3 protein expression by immunohistochemistry (IHC) in tumor and normal tissues was also performed." (PMID 26244168, 2015). "Positive IGF2BP3 cytoplasmic staining (1+ to 3+ intensity in >10% cells) was noted in 50% of the tumor specimens and 5% of the normal tissue specimens (1+ to 2+) intensity." (PMID 26244168, 2015). "IHC was carried out on paired tumor and normal tissue sections from 46 patients; IGF2BP3 staining was noted in 50% of the tumor sections and in 5% of the normal tissue sections." (PMID 26244168, 2015). "A previous study showed that IGF2BP3 expression significantly correlated with CD44s expression, and the expression levels of both IGF2BP3 and CD44s correlated with advanced tumor stage and grade in HCC." (PMID 26327240, 2015). "Specific IGF2BP3-bound transcripts—ARF6 and ARHGEF4—that are preferentially translated in membrane protrusions induce further formation of membrane protrusions; consequently, IGF2BP3 promotes cell invasiveness and tumor metastasis." (PMID 25216519, 2014). "Analysis of pancreatic xenograft tumors derived from control-RNAi S2-013 cells showed that cytoplasmic granular IGF2BP3 was mainly observed in the tumor penumbra, and ARF6 was strongly expressed near cell membranes in the penumbra." (PMID 25216519, 2014). "In contrast, each tumor derived from IGF2BP3-RNAi cells was largely encapsulated by host stromal cells and was apparently separated from normal pancreatic tissues." (PMID 25216519, 2014). "We expect that such analyses will indicate IGF2BP1 and IGF2BP3 as useful biomarkers for evaluating tumor aggressiveness and will reveal avenues to pursue analyzing their suitability for targeted therapy." (PMID 23677615, 2013). "Together, this suggests a fundamental role of IGF2BP1 and potentially IGF2BP3 in tumor cell dissemination, which presumably is observed in a broad variety of tumors." (PMID 23677615, 2013). "Nine (38%) patient samples of tumor grade 1 (n = 24) and 27 (44%) of tumor grade 2 (n = 61) showed expression of IGF2BP3." (PMID 20178612, 2010). "The Venn diagram shows that the expression levels of insulin-like growth factor 2 mRNA binding protein 1 (IGF2BP1), IGF2BP2 and insulin-like growth factor 2 mRNA binding protein 3 (IGF2BP3) were elevated in the tumor microarray data of HBL, and these genes were included in the m6A-related gene list." (PMID 40507253, 2025). "Thus, IGF2BP3 is one possible additional gene/protein in facilitating tumour development and metastasis in vivo." (PMID 40535577, 2025). "Additionally, IGF2BP3 aids in tumor cell proliferation by interacting with HNRNPM in the nucleus 23, thereby boosting cyclin protein expression." (PMID 40765570, 2025).
tumor (continued). "Through molecular docking, we found that BI-2536 was able to bind to IGF2BP3, which may provide a new molecular basis for its anti-tumor function." (PMID 40801655, 2025). "Our results suggest that targeting BRD family proteins may be a promising strategy for inhibiting IGF2BP3 expression and potentially affecting tumor progression in MCC and other cancers." (PMID 40162116, 2025). "In our research, the regulatory function of mechanic-m6A on YAP1 was identified in response to the PDAC heterogeneous stiffness, in which local stiff niches enhance YAP1 levels to boost the tumor cell stem-like type via METTL14/IGF2BP3-suppressed YAP1 mRNA decay." (PMID 40822927, 2025). "TRIP13 and IGF2BP3, which promote tumour growth, were also highly differentially accessible." (PMID 40946111, 2025). "Moreover, the overall m6A level and its related METTL3, METTL14, and WTAP protein levels, as well as cytoplasmic MALAT1-exporting IGF2BP3 and its distribution in xenograft tumor tissues, were increased in the HBx group." (PMID 40860202, 2025). "The findings imply that IGF2BP3 is essential for promoting tumor growth in vitro." (PMID 40530014, 2025). "This upregulation was positively correlated with larger tumor size, indicating that IGF2BP3 may contribute to CRC progression." (PMID 40765816, 2025). "Insulin-like growth factor 2 mRNA-binding protein 3 (IMP3) has been implicated in tumor biology, but its role in cellular metabolism is not well characterized." (PMID 41614778, 2025). "In vivo, IGF2BP3-KD suppressed tumor growth and reduced Ki67/SLC7A11 expression." (PMID 40530014, 2025). "This study further expands our understanding of IGF2BP3 in RNA metabolism and tumor progression." (PMID 40963905, 2025). "Furthermore, immune infiltration studies highlighted significant correlations between CDKN2B-AS1, IGF2BP3, and multiple immune cell types, suggesting that this axis regulates the tumor immune microenvironment." (PMID 39883704, 2025). "Together, our results suggest that IGF2BP3 and its target genes may contribute to tumor progression and serve as prognostic biomarkers for MCC." (PMID 40162116, 2025). "Therefore, in KIRC and various other cancers, IGF2BP3 utilizes its m6A-reading function to stabilize a cohort of oncogenic transcripts, thereby driving tumor proliferation, invasion, and metastasis." (PMID 41589308, 2025). "Furthermore, immunohistochemical analysis revealed that the downregulation of IGF2BP3 resulted in a significant decrease in Ki67 expression, a recognized indicator of tumor proliferation." (PMID 40530014, 2025). "Furthermore, our pan-cancer analysis revealed a significant association between BRD4 expression and metastasis and survival, underscoring the involvement of BRD4 and IGF2BP3 in tumor progression across various cancer types." (PMID 40162116, 2025). "Furthermore, simultaneous high expression of IGF2BP3 and OLFML1 was strongly associated with larger tumor size and advanced T stage in the TNM classification." (PMID 40765816, 2025). "Significantly, IGF2BP3 levels showed a link to tumor progression stage." (PMID 40801655, 2025). "In addition, METTL3 can promote PD-L1 mRNA stabilization by upregulating PD-L1 expression at the post-transcriptional level in an IGF2BP3-dependent manner, which is important for new and effective therapeutic strategies in tumor immunotherapy." (PMID 38577615, 2024). "Tumor cells with knock-out IGF2BP3 displayed increased apoptosis and reduced proliferation." (PMID 39342406, 2024). "IGF2BP3 was reported to be overexpressed in various kinds of tumor, indicating it might be the potential oncogene." (PMID 38448411, 2024). "Among these, IGF2BP3 exhibits high expression in various tumor tissues, such as lung cancer, gastric cancer, pancreatic cancer, kidney cancer, hepatocellular carcinoma, breast cancer, and ovarian carcinoma, in contrast to adjacent normal tissues, indicating its role in promoting tumorigenesis." (PMID 38504159, 2024).